GZMB (granzyme B)
Description:
Abundant protease in the cytosolic granules of cytotoxic T-cells and NK-cells which activates caspase-independent pyroptosis when delivered into the target cell through the immunological synapse. It cleaves after Asp. Once delivered into the target cell, acts by catalyzing cleavage of gasdermin-E (GSDME), releasing the pore-forming moiety of GSDME, thereby triggering pyroptosis and target cell death. Seems to be linked to an activation cascade of caspases (aspartate-specific cysteine proteases) responsible for apoptosis execution. Cleaves caspase-3, -9 and -10 (CASP3, CASP9 and CASP10, respectively) to give rise to active enzymes mediating apoptosis. Cleaves and activates CASP7 in response to bacterial infection, promoting plasma membrane repair (By similarity).
Synonyms: CTSGL1; HLP; CGL1; CSPB; CTLA1; CCPI; CGL-1; CSP-B; SECT; C11
Tractability: Small molecule: it has a binding pocket of medium quality; it belongs to a druggable protein family. Antibody: UniProt places it where antibodies can reach, with high confidence; UniProt predicts a signal peptide or a membrane-spanning region; its Gene Ontology location is reachable by antibodies, with medium confidence. PROTAC: its protein half-life has been measured; a small molecule that binds it is known.
Target class: Serine protease; Enzyme; Serine protease PA clan; Serine protease S1A subfamily; Protease
Gene: Protein-coding gene on chromosome 14 (24,630,954 to 24,634,267, reverse strand). Ensembl gene ENSG00000100453.
Subcellular location: Secreted; Cytolytic granule
Subcellular location (Human Protein Atlas): Calyx; Predicted to be secreted
Pathways (Reactome):
Programmed Cell Death: Activation, myristolyation of BID and translocation to mitochondria; Pyroptosis
Disease: Nuclear events stimulated by ALK signaling in cancer
Signal Transduction: NOTCH2 intracellular domain regulates transcription
Gene Ontology:
Molecular function: protein binding; serine-type endopeptidase activity; serine-type peptidase activity
Biological process: granzyme-mediated programmed cell death signaling pathway; natural killer cell mediated cytotoxicity; negative regulation of translation; protein catabolic process; protein maturation; pyroptotic inflammatory response; apoptotic process; positive regulation of establishment of protein localization to mitochondrion; proteolysis
Cellular component: cytolytic granule; cytoplasm; extracellular region; membrane; cytolytic granule lumen; cytosol; immunological synapse; nucleus
Genetic constraint (gnomAD): Loss-of-function variants: 27 observed, 25.58 expected, observed/expected ratio (o/e) 1.06, 90% interval 0.78 to 1.46. The upper end of that interval is the gene's LOEUF score, 1.46, which puts it in group 6 of 6, group 1 being the genes least tolerant of losing a copy. Missense variants: 335 observed, 313.11 expected, observed/expected ratio (o/e) 1.07, 90% interval 0.98 to 1.17. Synonymous variants: 120 observed, 113.72 expected, observed/expected ratio (o/e) 1.06, 90% interval 0.91 to 1.23.
Homologues: Orthologues: chimpanzee GZMB (98% identical), macaque GZMB (82% identical), pig GZMB (72% identical), rat Gzmbl3 (69% identical), mouse Gzmb (68% identical), rat Gzmbl1 (67% identical), mouse Gzmc (61% identical), rat Gzmbl3 (61% identical), rat Gzmc (59% identical), mouse Gzmd (57% identical), mouse Gzmg (56% identical), rat Gzmf (55% identical), and 6 more. Paralogues in human: GZMH (71% identical), CTSG (57% identical), CMA1 (53% identical), KLK13 (39% identical), KLK6 (36% identical), AZU1 (34% identical).
Diseases named in the same sentence as GZMB in open-access papers:
GZMB is named in the same sentence as 442 diseases in open-access papers, as found by Europe PMC text mining. Sharing a sentence is not in itself a finding about the gene and the disease. The quoted sentences say what the papers report.
melanoma (171 papers, 2007 to 2025). A malignant, usually aggressive tumor composed of atypical, neoplastic melanocytes. "By disrupting NF-κB and ERK1/2 signaling, melanoma-associated CAFs restrict CTL function, reducing granzyme B secretion and impairing their capacity to kill melanoma cells." (PMID 40399946, 2025). "Training on DCs impacted the functional shape of CD8 T cells infiltrating melanoma tumors, which displayed the expression of Ki67 and Granzyme B, associated with a higher expression of CD44, suggesting that these cells acquired a memory phenotype." (PMID 38812523, 2024). "It has been shown that upon full activation of CTLs, perforin accumulates more readily on the membrane of sensitive target cells than melanoma cells, which is associated with decreased accumulation of granzyme B inside the tumor cell." (PMID 35592329, 2022). "We have previously reported that genetic targeting of Becn1 in melanoma cells prevents the degradation of Natural killer (NK)-derived Granzyme B and enhances melanoma susceptibility to NK-mediated killing." (PMID 33718194, 2021). "A subset of cMet+ CD8+ T cells have been identified in murine tumor models and melanoma patients, where cMet expression is associated with increased cytolytic capacity and effector functions including IFNγ/TNFα and granzyme B/perforin production." (PMID 32545260, 2020). "Studies show surgical stress results in a reduction in the number of CD8+ T cells that produce cytokines (IFNγ, TNFα, and Granzyme B) in response to TAA (adenovirus expressing melanoma tumor-associated antigen)." (PMID 29201900, 2017). "In human melanoma, a higher expression of granzyme B in the stroma of the primary tumor is associated with a better outcome and a better response to immunotherapy." (PMID 27788481, 2016). "We also investigated the role of perforin and granzyme-B in the augmentation of 1H3-cell cytotoxicity against A02 melanoma cells associated with coexposure to the ABT-737 Bcl-2 inhibitor." (PMID 17311012, 2007). "Here we show that, on conjugation with CTL, human melanoma cells undergo an active late endosome/lysosome trafficking, which is intensified at the lytic synapse and is paralleled by cathepsin-mediated perforin degradation and deficient granzyme B penetration." (PMID 26940455, 2016). "In the Trp1-specific TCR-transgenic model, it was demonstrated that the rejection of B16 melanoma cells was abrogated in mice deficient for either granzyme B or perforin, indicating that these molecules are important for CD4+ T cell-mediated killing of MHC IIPOS tumor cells." (PMID 24782871, 2014). "Interestingly, training-induced by CTB promotes a highly co-stimulatory phenotype in tumor-infiltrating DCs (CD86+) and a heightened functionality of exhausted CD8 T cells (Ki67+, GZMB+), which were associated with a protective response against melanoma challenge in vivo." (PMID 38812523, 2024). "However, increased frequencies of CD8+ Teff (GZMB+EOMES+) at 6 months were associated with relapse in melanoma patients with Ipilimumab, suggesting that these cells might be terminally exhausted." (PMID 37881432, 2023). "Furthermore, LXR-mediated MDSC depletion with an LXR agonist was associated with a significant increase in IFN-γ and granzyme B positive TILs in vivo in mouse melanoma models, which enhanced the anti-tumour activity of anti-PD-1 therapy and significantly impaired tumour growth." (PMID 34944851, 2021). "However, it cannot detect the ROCKII activation mediated by proteolytic cleavage of the inhibitory C-terminal region by granzyme B in apoptotic cells, as well as the somatic mutation which leading to premature termination of translation at Y1174 identified in a malignant melanoma cell line." (PMID 26626121, 2015).
melanoma (continued). "We observed that DdBIC directly induced granzyme B expression and activity in melanoma cells, which is distinct from the commonly recognized T-cell-derived granzyme B, highlighting the cell-autonomous role of endogenous granzyme B in GSDMC cleavage." (PMID 41407678, 2025). "By combiningγδ-T exosomes and PDT, we achieved a robustantitumor effect from γδ-T exosome-derived cytolytic molecules,including granzyme A, granzyme B, perforin, and granulysin, and Ce6-mediatedROS generation inside melanoma cells." (PMID 39862206, 2025). "Here, we discovered a chemical compound, dodecyl 1H-benzo[d]imidazole-5-carboxylate (DdBIC), that targeted the nuclear receptor Nur77 to induce pyroptosis through cleaving GSDMC by granzyme B in melanoma cells." (PMID 41407678, 2025). "In summary, these findings establish that prodrug H62 activates the STING pathway in melanoma and NK cells, thereby enhancing NK cell cytotoxicity and promoting the secretion of key effector molecules, including perforin and granzyme B." (PMID 41239499, 2025). "For example, HDAC inhibition in aged CD8+ T cells restored IFN‐γ and granzyme B expression, resulting in enhanced melanoma control in mouse models." (PMID 40926366, 2025). "Functionally, these alterations lead to reduced granzyme B release and defective target recognition in melanoma‐bearing hosts." (PMID 40926366, 2025). "Following this, we conducted additional co-cultures with melanoma target cells to evaluate activation markers and granzyme B expression." (PMID 40181966, 2025). "Plasma‐derived PD‐L2+ EVs from patients with mucosal melanoma significantly reduced the frequency of granzyme B+ CD8 T cells within the peripheral blood mononuclear cells (PBMCs) of healthy individuals." (PMID 40135876, 2025). "Our findings indicate a positive correlation between tumor‐intrinsic IL4I1 expression and the expression of HLA‐A/‐B/‐C, B2M, and genes associated with CTL activation (GZMB, GZMA, CD8A, IFNG) in melanoma patients." (PMID 40583248, 2025). "In agreement, a positive correlation between CD8+ T‐cell reactivity markers such as CD8A (coding gene for CD8), PRF1 (as Perforin), GZMB (coding gene for Granzyme B) and ERRα was observed, as indicated by co‐expression analyses in different melanoma databases." (PMID 39888245, 2025). "The results demonstrated that, in the activated state, CM from Vin-treated melanoma cells similarly enhanced the expression of IFNγ, GZMB, IL-2, and TNFα in Jurkat cells." (PMID 40866941, 2025). "Mechanistically, we find inhibition of Notch1 increases CD8+ T cell degranulation and IFNγ and Granzyme B production both in vitro and in vivo, leading to melanoma cell killing." (PMID 39491031, 2024). "In the tumor microenvironment, reprogrammed lipid metabolism plays a crucial role in improving the efficacy of immunotherapy by upregulating IFN-γ and granzyme B in mouse melanoma models." (PMID 39543650, 2024). "Next, to identify the role of Mi-2β in the immune response in melanoma, the correlation between Mi-2β and GZMB or PRF1 was analyzed." (PMID 38461299, 2024). "It was demonstrated that TIL positive for the CD8+ T cell effector molecule called Granzyme B (GZMB) was linked to longer O and progression-free survival (PFS) in the Stage II primary melanoma tumors cohort." (PMID 39712007, 2024). "Activation of TLR1/2 promotes the effector activity of CD8+ T cells in B16 melanoma cells both in vivo and in vitro through upregulation of perforin, Granzyme B, IFNγ and TNF-α." (PMID 37936697, 2023). "Surprisingly, whereas TKO NK cells isolated from B16 melanoma cells had a reduced lytic potential, the same cells showed increased granzyme B accumulation when isolated from MCMV infected tissues." (PMID 37520575, 2023). "Paired sc-RNA and sc-TCR-seq analysis of melanoma patient specimens demonstrated that clonal T cells in periphery are in a more activated cellular state (CCL5+GZMB+KLRG1+KLRK1+CX3CR1+) than their counterparts in TME (PD-1+LAG3+CTLA-4+TIM-3+TIGIT+)." (PMID 37881432, 2023).
melanoma (continued). "Topical imiquimod application in a melanoma mouse model reduces Treg cell-related chemokine mRNA expression and increases cytotoxic molecules like granzyme B and perforin within tumors." (PMID 37936697, 2023). "Our result demonstrated CAR-T cell-specific activity reflected by the elevation of both interferon-gamma and Granzyme B in EpCAM+ gastric-PDXO-GA0091 co-culture as compared to the EpCAM- melanoma PDXO-ME1154 co-culture." (PMID 36602988, 2023). "As such, we validated our cytotoxicity assay and documented that overexpression of SERPINB9, a natural inhibitor of granzyme B, in melanoma target cells rendered them resistant to NK-92 cytotoxicity." (PMID 36380966, 2022). "These authors found that manipulating LDHA levels in a mouse model of melanoma results in more infiltrating NK cells and greater expression of IFNγ and granzyme B and greater tumor control in low-LDHA tumors compared to controls." (PMID 35414042, 2022). "Consistently, melanoma patients with higher level expression of STAT3 or GZMB suggested a good prognosis." (PMID 35145233, 2022). "Intravenous WT and B2m-/- B16 melanoma challenge resulted in a significant increase in the proportions of granzyme B/perforin positive IVneg NK cells in the lungs." (PMID 36733396, 2022). "The infiltration of the TME by CD8+ cells and the production of granzyme B and IFNγ have been correlated with decreased metastatic invasion and improved melanoma treatment responses." (PMID 36923305, 2022). "claimed YTHDF2 can control melanoma metastasis by promoting NK cells to secret perforin, granzyme B, and IFN-γ in the tumour environment." (PMID 35572541, 2022). "By analysis of SKCM-TCGA data, we also found a positive correlation between STAT3 and GZMB expression in human melanoma." (PMID 35145233, 2022). "In this melanoma sample, expression of genes associated with the terminally differentiated phenotype of CD8+ T cells, such as HAVCR2 (TIM-3), LAG3, CXCL13, and GZMB, was highest in the tumor parenchyma adjacent to inflammation." (PMID 35584630, 2022). "We further showed that eEF2K promotes stabilization of PD-L1 protein through its interaction with GSK3β, and that knockdown of eEF2K decreased PD-L1 expression and increased CD8+ T cell number and granzyme B (GZMB) in tumor tissues in a mouse melanoma model." (PMID 35347072, 2022). "Accordingly, terminally exhausted TILs in melanoma patients demonstrated reduced proliferative capacity, but profound anti-tumor cytotoxic activity, probably due to elevated levels of granzyme B." (PMID 35406703, 2022). "Lower expression of HLA-class I on melanoma cells is associated with poor infiltration of CD45RO+, CD8+, Granzyme B+ T cells and hence probable cause of tumor escape, and therapy resistance." (PMID 33436641, 2021). "Others believed that CD4+ GZMB+ T cells mediated the recruitment of immune cells in melanoma through the release of inflammatory cytokines and chemokines, which would explain the increase infiltration of immune cells in the central tumor." (PMID 34631551, 2021). "Incubation of ex vivo activated human T cells with PDI-1 enhanced their cytotoxicity towards human lung cancer and melanoma cells, and concomitantly increased the production of granzyme B, perforin, and inflammatory cytokines." (PMID 34054817, 2021). "Beyond CMS2 CRC, GZMB expression was also observed in melanoma tumor cell lines across a broader cell line panel covering 12 cancer types." (PMID 34972191, 2021). "Although not significant, CD patients also showed a trend for a higher frequency of melanoma cells within a 30 μm radius from CD8 + Granzyme B+ activated CTL than PD patients." (PMID 33947438, 2021). "The expresson level of CD8+ T cells markers including CD8A, GZMB, NKG7, etc., was all shown to be higher in low risk melanoma patients." (PMID 34040608, 2021). "DHA enhanced apoptosis of melanoma by regulating FasL expression and Granzyme B secretion in CD8+CTLs." (PMID 34539408, 2021).
melanoma (continued). "Enhanced immune recognition would lead to activation of Pmel-1 T cells resulting in acquisition of effector function (increased cytokine production, perforin and Granzyme B secretion) and lysis of melanoma cells." (PMID 32231230, 2020). "In a cohort of primary melanoma tumors (Stage II), it was shown that the presence of TIL positive for the CD8+ T cell effector molecule Granzyme B (GZMB) were associated with longer progression-free survival (PFS) and OS." (PMID 33013886, 2020). "Activation of the signalling pathways associated with acute phase response, granzyme B, IL15, the upstream modulator, HSP90B1 and inhibition of the upstream modulator EOMES also indicated immune related mechanisms in development of melanoma metastasis." (PMID 33142795, 2020). "MSCs, transplanted 14 days after melanoma induction, attenuated tumoricidal capacity of NK cells, as evidenced by the lower number of tumor-infiltrating granzyme B-expressing NK1.1+ cells in B16F10+MSCs14d-treated mice (p < 0.05)." (PMID 32695181, 2020). "Our results indicate that after cell-contact-permissive co-cultures with hypoxic B16F10-Cx43WT cells, pMEL-1 CTLs triggered less caspase and granzyme b activities in target melanoma cells than after co-culture with normoxic or hypoxic B16F10-Cx43DN cells." (PMID 33066331, 2020). "As observed in the melanoma tumor model, Tα1 increased the expression of CD8-associated markers (GzmB and Perforin) while reducing the recruitment of Foxp3+CD25+ Treg cells in the lung in combination with anti-PD1 antibody." (PMID 32817121, 2020). "We used triple-color immunohistochemistry to evaluate Foxp3 and GzmB expression in CD4+ TILs in patients with advanced melanoma prior to therapy and 3 weeks post-treatment with ipilimumab and melphalan." (PMID 31924474, 2020). "Of note, B16F10 melanoma cells co-cultured with perforin/GzmB knock out mice (KO) MDSCs displayed a remarkable decrease in invasive potential." (PMID 31212684, 2019). "These cells produced enhanced levels of IFN-γ and granzyme B and were capable of killing melanoma cells." (PMID 30560089, 2018). "Additionally, anti-IL-20R2 treatment reduced the expression of IFNγ, GZMB, IL-2, and TNFα in Jurkat cells co-cultured with Vin-treated melanoma cells." (PMID 40866941, 2025). "Sodium chloride (high-salt diet, HSD) exhibits context-dependent modulation of the axis: HSD suppresses MDSC function via p38/MAPK-NFAT5 signaling, expanding cytotoxic NK cells and enhancing CD8+ T cell effector function (IFN-γ, granzyme B) to boost anti-PD-1 efficacy in melanoma and CRC models." (PMID 41181090, 2025). "Additionally, the TCR-KI T cells released granzyme B when incubated with melanoma FM72, which is a very good target of the MC.7.G5 TCR and MR1*01 homozygous, but also at very reduced levels of activation compared with the TCR-replaced T cells." (PMID 39744940, 2025). "Additionally, RT-PCR analysis showed that Jurkat cells co-cultured with Vin-treated melanoma cells exhibited significantly higher mRNA levels of IFNγ, GZMB, IL-2, and TNFα in the activated state." (PMID 40866941, 2025). "However, BPC‐Panx1KO mice displayed splenomegaly and an increase of effector T lymphocytes and granzyme B+ cells (GzmB+) in the melanoma tumor microenvironment." (PMID 38327091, 2024). "Increased numbers of GZMB+ cells in the TIME have been linked to a favorable prognosis in some tumors including cervical intraepithelial neoplasia, oral squamous cell carcinoma, and melanoma." (PMID 39643914, 2024). "Also consistent with our results with SkOV3-CD19, we show that A375-CD19 melanoma cells are sensitive to combined FasL and GZMB inhibition, since it is already known that Fas expression of A375 is comparable to SkOV3." (PMID 38307835, 2024). "To determine whether the increased IFN-γ and granzyme-B expression in CD8 T cells was associated with antigen-specific T cell responses, we examined the presence of melanoma-specific CD8 T cells with H-2Db gp100 tetramer." (PMID 38424542, 2024).